ZNF839 (zinc finger protein 839)
Synonyms: C14orf131
Tractability: Antibody: the Human Protein Atlas places it where antibodies can reach. PROTAC: ubiquitination databases record sites on it.
Gene: Protein-coding gene on chromosome 14 (102,317,377 to 102,342,702, forward strand). Ensembl gene ENSG00000022976.
Subcellular location (Human Protein Atlas): Plasma membrane; Nucleoplasm
Pathways (Reactome):
Gene expression (Transcription): Generic Transcription Pathway
Genetic constraint (gnomAD): Loss-of-function variants: 37 observed, 52.13 expected, observed/expected ratio (o/e) 0.71, 90% interval 0.55 to 0.93. The upper end of that interval is the gene's LOEUF score, 0.93, which puts it in group 3 of 6, group 1 being the genes least tolerant of losing a copy. Missense variants: 1,085 observed, 1,134.1 expected, observed/expected ratio (o/e) 0.96, 90% interval 0.91 to 1.01. Synonymous variants: 480 observed, 475.23 expected, observed/expected ratio (o/e) 1.01, 90% interval 0.94 to 1.09.
Homologues: Orthologues: chimpanzee ZNF839 (92% identical), macaque ZNF839 (91% identical), dog ZNF839 (62% identical), mouse Zfp839 (51% identical), rat Zfp839 (51% identical), zebrafish znf839 (23% identical), tropical clawed frog znf839 (21% identical).
Diseases named in the same sentence as ZNF839 in open-access papers:
ZNF839 is named in the same sentence as 6 diseases in open-access papers, as found by Europe PMC text mining. Sharing a sentence is not in itself a finding about the gene and the disease. The quoted sentences say what the papers report.
breast carcinoma (1 paper, 2019). "It is reported that MYH6 and ZNF839 are associated with breast cancer." (PMID 31888641, 2019).
ovarian carcinoma (1 paper, 2021). A malignant neoplasm originating from the surface ovarian epithelium. "Meanwhile, our findings revealed that MRC2, LASP1, and ZNF839 were upregulated in ovarian cancers, especially in the subtype of serous ovarian cancer." (PMID 34336102, 2021). "Altogether, our findings demonstrated that LINC00909 is a ceRNA of MRC2, LASP1, and ZNF839 mRNA in the mediation of miR-23b-3p in ovarian cancer cells." (PMID 34336102, 2021). "Interestingly, we found that, in the ovarian cancer RNA expression datasheet from the GEPIA database, ZNF839, DEPDC1, and MRC2 were associated with LINC00909 in the RNA level." (PMID 34336102, 2021).
ZNF839 also shares sentences with these, for which no sentence is quoted: atherosclerosis (1 paper); atrial septal defect 3 (1); familial hypertrophic cardiomyopathy (1); serous ovarian cancer (1).